RNU6-909P (RNA, U6 small nuclear 909, pseudogene)
Gene: Small nuclear RNA gene on chromosome 5 (28,624,657 to 28,624,763, forward strand). Ensembl gene ENSG00000252867.
Homologues: Orthologues: chimpanzee U6 (99% identical), macaque U6 (94% identical), mouse Gm24131 (64% identical), dog U6 (59% identical), pig U6 (57% identical), rat LOC120096102 (54% identical). Paralogues in human: RNU6-424P (73% identical), RNU6-16P (72% identical), RNU6-214P (72% identical), RNU6-312P (72% identical), RNU6-449P (72% identical), RNU6-80P (72% identical), RNU6-818P (72% identical), RNU6-883P (72% identical), RNU6-936P (72% identical), RNU6-1103P (71% identical), RNU6-1145P (71% identical), RNU6-1227P (71% identical), and 1284 more.